CUL7 (cullin 7)
Diseases named in the same sentence as CUL7 in open-access papers (continued):
Sharing a sentence is not in itself a finding about the gene and the disease.
breast carcinoma (continued). "Furthermore, the upregulation of CUL7 has been revealed in multifarious malignant tumours, such as hepatocellular carcinoma, epithelial ovarian cancer, lung cancer, breast cancer, and choriocarcinoma; thus, there is a good chance that CUL7 plays an important role in tumour progression." (PMID 32252802, 2020). "In addition, CUL7 overexpression and unfavourable prognosis have been reported to be correlated in hepatocellular carcinoma, epithelial ovarian cancer, lung cancer, breast cancer, and choriocarcinoma." (PMID 32252802, 2020). "For example, CUL7 promotes the survival of a variety of cancer cells, including MDA-MB-231 breast cancer cells, HeLa cells and HEK293T cells, by promoting caspase-8 ubiquitination." (PMID 32252802, 2020). "Importantly, CUL7 has not previously been reported in breast cancer." (PMID 25146004, 2014).
glioma (6 papers, 2020 to 2025). A benign or malignant brain and spinal cord tumor that arises from glial cells (astrocytes, oligodendrocytes, ependymal cells). "High Cul7 expression has been associated with high tumor grade, mesenchymal molecular glioma subtype, and poor prognosis in glioma patients." (PMID 39852134, 2024). "In this study, we demonstrated that CUL7 acted as a novel oncogene associated with NF-κB activation in glioma, and we investigated its relationship with miR-3940-5p, a microRNA that has been reported to inhibit cell proliferation." (PMID 32252802, 2020). "High CUL7 expression was associated with a high tumour grade, a mesenchymal molecular glioma subtype and a poor prognosis in patients." (PMID 32252802, 2020). "In conclusion, our study highlighted that increased CUL7 expression levels were associated with a higher tumour grade, a mesenchymal subtype and a poor prognosis in human gliomas." (PMID 32252802, 2020). "Taken together, these results suggest that loss of CUL7 suppressed cell cycle progression and caused apoptosis in human glioma cells." (PMID 32252802, 2020). "Additional studies confirmed CUL7’s role in promoting glioma cell proliferation, migration, and invasion." (PMID 40260289, 2025). "CUL7, an E3 ubiquitin ligase, promotes glioma invasion by activating the NF-κB pathway, and its high expression is significantly associated with poor patient prognosis." (PMID 40130175, 2025). "Previous research highlighted CUL7’s presence in glioma, particularly the mesenchymal subtype, with patients exhibiting high CUL7 expression experiencing lower OS rates." (PMID 40260289, 2025). "Mechanistic investigations further revealed that CUL7 enhances glioma cell growth through MST1 ubiquitination and NF-κB pathway activation." (PMID 40260289, 2025). "To test this finding, we verified that downregulation of CUL7 inhibited the proliferation, migration and invasion of glioma cell lines in vitro and in vivo." (PMID 32252802, 2020). "In the Transwell assays, the number of migrated or invaded glioma cells in the CUL7 overexpression groups was increased compared with that in the control groups." (PMID 32252802, 2020). "The EdU assay showed that the effects of miR-3940-5p on glioma proliferation were counteracted by CUL7 overexpression." (PMID 32252802, 2020). "CUL7 silencing in glioma cells inhibited proliferation through cell cycle arrest at G0/G1 and induced cell apoptosis and reduced growth in orthotopic xenografts." (PMID 32252802, 2020). "CUL7 facilitated the proliferation, invasion and migration of glioma cells by influencing MST1 ubiquitination and activation of NF-κB pathways." (PMID 32252802, 2020). "CUL7 silencing appeared to specifically suppress the progression of EMT in glioma cells, which reduced their invasion abilities." (PMID 32252802, 2020). "To understand the function of CUL7 in glioma development, we first analysed the mRNA levels of CUL7 in glioblastoma (GBM) tissues and normal brain tissues from the TCGA dataset." (PMID 32252802, 2020). "To directly assess the role of CUL7 in glioma cell survival and proliferation, we performed EdU and CCK-8 assays in cells that were or were not transfected with siRNA." (PMID 32252802, 2020). "Our findings indicate that CUL7 plays a significant role in promoting tumorigenesis via NF-κB activation and that it can be negatively regulated by miR-3940-5p in human gliomas." (PMID 32252802, 2020). "Next, a series of experiments were performed to assess the role of CUL7 in several cellular processes of human glioma cells." (PMID 32252802, 2020).
glioma (continued). "GSEA based on CUL7 expression in the TCGA database was performed to explore the potential biological functions of CUL7 in gliomas." (PMID 32252802, 2020). "In our study, p21 and p27, which were identified as cyclin-dependent kinase inhibitors, were present in higher amounts in the si-CUL7 group in gliomas than in the controls." (PMID 32252802, 2020). "Using western blotting, we observed that several mesenchymal markers, such as N-cadherin, Vimentin and Slug, were decreased and that an epithelial factor (E-cadherin) was increased after CUL7 depletion in gliomas." (PMID 32252802, 2020). "In this way, to attain the potential molecular mechanisms by which CUL7 promotes glioma development, we detected the expression changes of some key mediators of cell proliferation and apoptosis, including p21, p27, cyclin D1, CDK4, cyclin E1 and CDK2." (PMID 32252802, 2020). "To investigate the regulatory mechanism of CUL7 in glioma progression, we used GSEA to explore the potential pathways of CUL7 and found that CUL7 was positively associated with the NF-κB pathway." (PMID 32252802, 2020). "Conversely, CUL7 silencing inhibited NF-κB activation and prevented growth of glioma cells." (PMID 36778118, 2023). "Similarly, the results of the Transwell invasion assays also revealed that CUL7 silencing reduced the number of glioma cells invading the Matrigel-coated membrane compared with that in the control groups." (PMID 32252802, 2020). "Furthermore, modified U87MG luciferase cells were implanted in nude mice orthotopically to verify the function of CUL7 in gliomas in vivo." (PMID 32252802, 2020). "Furthermore, CUL7 expression was confirmed as an independent indicator of OS in glioma after multivariate Cox regression analysis (HR = 3.084, 95% CI = 1.918 to 4.959, P < 0.0001)." (PMID 32252802, 2020). "Finally, CUL7 was found to be downregulated by miR-3940-5p, which suppressed the development of gliomas." (PMID 32252802, 2020). "Moreover, the miR-3940-5p expression level was significantly lower in glioma than in normal brain, which was opposite to the trend in CUL7 expression level." (PMID 32252802, 2020). "In this regard, we conducted searches to identify miRNAs that might regulate CUL7 based on bioinformatic analysis and found that miR-3940-5p negatively regulated the expression of CUL7 in glioma cells." (PMID 32252802, 2020). "Furthermore, Transwell assays showed that the effects of miR-3940-5p on glioma migration and invasion were counteracted by CUL7 overexpression." (PMID 32252802, 2020). "In this study, we showed that CUL7 was highly expressed in gliomas, especially in mesenchymal subtypes, and found that the expression of CUL7 increased as the overall survival of patients decreased, which demonstrated that CUL7 plays a significant role in the malignancy of glioma." (PMID 32252802, 2020). "Interestingly, qRT-PCR and western blotting demonstrated that overexpression of miR-3940-5p (via miR-3940-5p mimics transfected into cell lines after 48 h) induced a strong decrease in CUL7 expression in glioma cell lines." (PMID 32252802, 2020). "Collectively, the miR-3940-5p/CUL7/ NF-κB pathway may be a novel candidate therapeutic target in glioma treatment." (PMID 32252802, 2020). "Moreover, the protein levels of CUL7 were examined by immunohistochemical staining in an unconnected cohort of glioma and normal brain tissue samples from Qilu Hospital." (PMID 32252802, 2020). "Our results revealed that overexpression of miR-3940-5p could reduce the expression of CUL7 and inhibit proliferation, invasion and migration in gliomas." (PMID 32252802, 2020). "Additionally, we identified that CUL7 is a direct target of miR-3940-5p and that there is a suppressive role of miR-3940-5p in proliferation, invasion and migration in glioma cells." (PMID 32252802, 2020). "Moreover, in our study, CUL7 overexpression promoted the progression of EMT in glioma cells." (PMID 32252802, 2020).
glioma (continued). "Thus, high CUL7 expression was correlated with an increased tumour grade in glioma patients." (PMID 32252802, 2020). "In addition, whether CUL7 is involved in the proliferation, apoptosis, invasion and migration of glioma remains unknown." (PMID 32252802, 2020). "Moreover, CUL7 overexpression promoted proliferation in glioma cells in our study." (PMID 32252802, 2020). "Furthermore, CUL7 might be a candidate molecular target for the treatment of glioma." (PMID 32252802, 2020). "Correspondingly, the expression of the CUL7 protein was higher in high-grade gliomas (WHO III-IV; n = 21) than in normal brain tissues (n = 4) and low-grade gliomas (WHO I-II; n = 17)." (PMID 32252802, 2020). "Therefore, CUL7 might be a novel prognostic biomarker in gliomas." (PMID 32252802, 2020). "Here, we observed that CUL7 depletion significantly reversed EMT features and decreased invasiveness in glioma cells." (PMID 32252802, 2020). "To further confirm that miR-3940-5p inhibits cell proliferation, migration and invasion of glioma by targeting CUL7, we restored CUL7 expression by transfecting U87MG and U251 glioma cells with full-length CUL7 plasmids." (PMID 32252802, 2020). "However, the expression level and clinical significance of CUL7 in human gliomas has not been confirmed." (PMID 32252802, 2020). "The expression level of CUL7 was significantly higher (> median value) in the mesenchymal subtype than in the proneural subtype, and the ROC curve further showed the sensitivity of CUL7 as a marker to discriminate between the mesenchymal subtype and the non-mesenchymal subtype glioma patients." (PMID 32252802, 2020).
hepatocellular carcinoma (5 papers, 2020 to 2024). A malignant tumor that arises from hepatocytes. "In a 2013 study, the expression of Cul7 in hepatocellular carcinoma (HCC) cell lines and five different tissue samples was determined by quantitative reverse transcription PCR and Western blot method." (PMID 39852134, 2024). "Interestingly, a recent study reported a pro-fibrotic role of Cul7 in patients with hepatocellular carcinoma and amplification of the 6p21.1 gene locus." (PMID 33351822, 2020). "CUL7, a new gene reported in 2013, is closely related to the occurrence of hepatocellular carcinoma (HCC)." (PMID 36304472, 2022).
colorectal cancer (4 papers, 2022 to 2026). A primary or metastatic malignant neoplasm that affects the colon or rectum. "In colorectal cancer, CUL7 was overexpressed in tumor tissues by IHC with a mutation frequency of about 4%." (PMID 36304472, 2022). "CUL7 is an independent prognostic factor for colorectal cancer." (PMID 36304472, 2022).
lung carcinoma (4 papers, 2019 to 2024). "To date, the effect of CUL7 on the invasion and metastasis of neuroblastoma, lung cancer, and pancreatic cancer is unknown, suggesting that further research is still needed to explore the relationship between CUL7 and the progression of these tumors." (PMID 33130829, 2020).
liver cancer (3 papers, 2018 to 2024). An epithelial or non-epithelial malignant neoplasm that arises from the liver. "CUL7 also promotes epithelial-mesenchymal transformation of liver cancer and its high expression in liver tumors is associated with poor prognosis." (PMID 29594129, 2018). "Liu G showed that CUL7 can promote epithelial-mesenchymal transition in liver cancer, and its high expression in liver tumors is related to poor prognosis." (PMID 35463358, 2022). "The results of this study helped to elucidate the oncogenic functions of Cul7 in liver cancer." (PMID 39852134, 2024).
pancreatic cancer (3 papers, 2016 to 2024). "Cul7, which acts as a scaffold protein in the E3 ligase complex, is thought to have a potential oncogenic role in pancreatic cancer by promoting the proliferation of pancreatic cancer cells." (PMID 39852134, 2024). "Previous studies showed that targeted degradation of HPK1 in pancreatic cancer by the CUL7/Fbxw8 ubiquitin ligase involves HPK1 autophosphorylation." (PMID 27023625, 2016). "Moreover, CUL7, as the scaffold protein in the E3 ligase complex, promotes the proliferation of pancreatic cancer cells, suggesting a potential oncogenic role in pancreatic cancer." (PMID 33130829, 2020).
colon adenocarcinoma (2 papers, 2022 to 2024). "In this study, the expression of CUL7 in colon adenocarcinoma (COAD) was investigated to determine its prognosis value." (PMID 36304472, 2022).
epithelial ovarian cancer (2 papers, 2024). "Analysis of paraffin blocks of tissue samples from 120 epithelial ovarian cancer patients found that the expression level of Cul7 was significantly associated with tumor stage and lymph node metastasis in these patients and was a remarkable predictor of poor clinical prognosis." (PMID 39852134, 2024). "Cul7 is highly expressed in many malignant tumors, including lung, liver, breast, and ovarian cancers, and its expression is known to be closely related to clinical staging and prognosis." (PMID 39852134, 2024).
esophageal cancer (2 papers, 2024). A primary or metastatic malignant neoplasm involving the esophagus. "In the immunohistochemistry study of 130 patients with esophageal cancer, the expression of Cul7 in paraffin block tissue samples obtained was found to be significantly higher than in non-tumor tissues (p = 0.000)." (PMID 39852134, 2024).
glioblastoma (2 papers, 2020 to 2021). The most malignant astrocytic tumor (WHO grade IV).
growth disorder (2 papers, 2015 to 2019). "It is thought that 3M-growth syndrome is caused by a deficiency in protein turnover due to the finding that a majority of patients with 3M-growth disorder display mutations in cullin-7, Obsl1, and Ccdc8." (PMID 31098411, 2019). "Recently, exome sequencing has been used to reveal a mutation in the CUL7 gene in a young adult with a previously undiagnosed growth disorder." (PMID 25923536, 2015).
metastatic cancers (2 papers, 2020 to 2024). A carcinoma which has spread from the original site of growth to another anatomic site. "It has revealed that Cul7 promoted cell growth, invasion, and metastasis in many of these tumors, might play an oncogenic role in cancer, and had the potential to be used as a biomarker for the prognosis of metastatic cancers." (PMID 39852134, 2024).
osteosarcoma (2 papers, 2017 to 2024). A usually aggressive malignant bone-forming mesenchymal neoplasm, predominantly affecting adolescents and young adults. "Another CRL potentially interesting in the context of osteosarcoma is CUL7, which upon NEDDylation, is known to play an oncogenic role in other cancers, due to the upregulation of the EMT, as well as the induction of cell growth and invasion." (PMID 38534381, 2024). "Direct evidence about the role of CUL7 in osteosarcoma is still missing, so further research on CUL7 is needed to uncover a new potential therapeutic target." (PMID 38534381, 2024). "Among the other six Cullins, only CUL4A was slightly overexpressed (~1.4–1.7-fold induction) in osteosarcoma cells, but not the other five Cullins, including CUL1, CUL2, CUL3, CUL5 and CUL7." (PMID 28446751, 2017).
primordial dwarfism (2 papers, 2015 to 2023). "5.3% (2/38) of the fetuses harbored variants in CUL7 diagnosed with 3-M syndrome 1, which would lead to primordial dwarfism." (PMID 36923788, 2023). "Indeed, a relationship between CUL7 and CtIP has been recently shown in terms of pathology, as specific mutations in either gene are associated with primordial dwarfism with similar phenotypes." (PMID 25567988, 2015).
autism (1 paper, 2021). Persistent deficits in social interaction and communication and interaction as well as a markedly restricted repertoire of activity and interest as well as repetitive patterns of behavior. "Additionally, we observed an enrichment (FDR = 0.015) for candidate autism genes, including FOXP1, CUL7, ANK3, and EP300, among the differentially expressed genes." (PMID 34657631, 2021).
cardiac hypertrophy (1 paper, 2020). "To determine the impact of genetic ablation of Cul7, thereby disrupting the CRL7 ubiquitin ligase complex, on cardiac fibrogenesis, we performed transverse aortic constriction (TAC), a well-established animal disease model for pressure overload-induced cardiac hypertrophy and fibrosis." (PMID 33351822, 2020).
colon cancer (1 paper, 2025). "Additionally, RT-PCR confirmed the association of CUL7, ENO2, and MPP2 expression levels with colon cancer." (PMID 40260289, 2025). "CUL7, ENO2, and MPP2 were identified as potential antigens for colon cancer mRNA vaccines, with MPP2 showing particular immunological relevance." (PMID 40260289, 2025). "Thus, This study identifies CUL7, ENO2, and MPP2 as potential antigens for colon cancer mRNA vaccines." (PMID 40260289, 2025).
Hypergonadotropic hypogonadism (1 paper, 2024). Reduced function of the gonads (testes in males or ovaries in females) associated with excess pituitary gonadotropin secretion and resulting in delayed sexual development and growth delay. "Only 1 case of a male CUL7 pathogenic variant carrier with hypergonadotropic hypogonadism has so far been reported." (PMID 38847008, 2024). "We present a case of a male with a CUL7 pathogenic variant who underwent an unsuccessful trial of rhGH treatment and showed pubertal arrest with evidence of hypergonadotrophic hypogonadism." (PMID 38847008, 2024).
hypogonadism (1 paper, 2024). A disorder characterized by decreased function of the gonads. "CUL7 pathogenic variant carriers in the Yakuts population did not demonstrate hypogonadism, and hypospadias was observed only in 1 case." (PMID 38847008, 2024).
Interstitial cardiac fibrosis (1 paper, 2020). A type of myocardial fibrosis characterized by excessive diffuse collagen accumulation concentrated in interstitial spaces. "After transverse aortic constriction (TAC), causing chronic pressure overload and fibrosis, AAV9-CMV-iCre induced Cul7-/- mice displayed a ~50% reduction of interstitial cardiac fibrosis when compared to Cul7+/+ animals (6.7% vs. 3.4%, p<0.01)." (PMID 33351822, 2020).